ALB (albumin)
Diseases named in the same sentence as ALB in open-access papers (continued):
Sharing a sentence is not in itself a finding about the gene and the disease.
malnutrition (continued). "Renewed focus on the use of suitable biochemical markers of malnutrition resulted in the recommendation of serum transthyretin, otherwise known as prealbumin, as a more sensitive nutrition marker than albumin and transferrin due to its shorter half-life." (PMID 38379550, 2024). "Decreased blood albumin levels are a well-known clinical indication of malnutrition, resulting in weakened respiratory muscles and diminished lung function." (PMID 39026682, 2024). "Low levels of ALB not only indicates malnutrition, but also is related to inflammatory reaction, which can increase the risk of circulatory thromboembolism, and is a common biomarker for risk stratification of cardio-cerebrovascular diseases." (PMID 39726875, 2024). "Other outcome parameters not investigated in this review are need for and length of PN, malnutrition, albumin and prealbumin levels, duration of analgesia, feeding intolerance, 30-day mortality or readmission rates, and weight for age Z-score (WAZ)." (PMID 39678118, 2024). "This leads to a decline in hemoglobin and albumin levels, resulting in malnutrition, anemia, and a compromised immune system." (PMID 39042620, 2024). "Albumin is a valuable biomarker for assessing malnutrition, as demonstrated in a meta-analysis evaluating 43 blood markers." (PMID 39203760, 2024). "Patients with malnutrition had lower BMI, albumin levels, and higher APACHE II compared with well-nourished patients." (PMID 38799151, 2024). "Weight and BMI, preoperative albumin and malnutrition, functional status, and history of CHF varied significantly by preoperative weight loss (P < 0.05 for all)." (PMID 38561849, 2024). "For instance, nutritional status such as obesity and malnutrition, laboratory values of albumin and sodium, and fluid status significantly influence this process and psychological status." (PMID 39459466, 2024). "Meanwhile, malnutrition, which is constantly present in such cases, is translated through a low serum level of albumin." (PMID 39061143, 2024). "In conclusion, this study’s primary findings indicate that malnutrition identified using the simplified GLIM is associated with age, CDAI, behavior, hemoglobin, and albumin, providing prognostic value for endoscopic remission in CD patients." (PMID 39850334, 2024). "Inflammation is a relevant issue for the correct diagnosis of malnutrition as its presence detracts significance to albumin levels." (PMID 38805173, 2024). "Predictive value of serum GDF15 levels, serum ALB levels and their combination in malnutrition patients with AECOPD." (PMID 39050134, 2024). "The Italian second dish is principally made of protein, and albumin, which is the most abundant protein in human serum, has been used for decades as an indicator of malnutrition in patients in clinically stable conditions." (PMID 39519422, 2024). "We also observed that decreases in hemoglobin and albumin levels correlated with lower MoCA scores, reflecting the impact of anemia and malnutrition in CKD on brain oxygenation and metabolism, exacerbating cognitive impairment." (PMID 39335505, 2024). "Keywords sought included hypoalbuminemia, serum albumin, malnutrition, hip fractures, neck of femur fractures, wound infections, and post-operative complications." (PMID 38817798, 2024). "Serum albumin levels below 3.0 g/L are accepted as critical values indicative of significant malnutrition." (PMID 39456817, 2024). "Somewhat surprisingly, perioperative anaemia was recorded in a number of patients (41.9%), often correlating with a low albumin value (average value 32.6 g/L), possibly indicating malnutrition, aging, or a chronic disease state." (PMID 38731106, 2024). "The interplay between albumin and fibrinogen levels in the context of inflammation and malnutrition further complicates the prognostic landscape for PD patients." (PMID 39281816, 2024).
malnutrition (continued). "Multivariable logistic regressionanalysis revealed that anemia (odds ratio [OR], 1.76; 95% confidence interval[CI], 1.07–2.90) and serum albumin (OR, 0.55; 95% CI, 0.50–0.60) were theindependent predictors for malnutrition." (PMID 39139423, 2024). "Patients at risk of malnutrition demonstrated elevated WBC counts, NLR, and INR, along with reduced levels of albumin, total protein, and cholesterol (all p < 0.03)." (PMID 39125277, 2024). "The assessment of malnutrition status in this category of patients can be conducted using indices such as serum albumin or BMI." (PMID 39728053, 2024). "A severe malnutrition emerged from BMI, low plasma pre-albumin, albumin, transferrin, and creatinine." (PMID 38888722, 2024). "Our study confirms how albumin is an important measurable indicator of nutritional status and how malnutrition determines low serum lymphocyte values, which contributes to poor clinical outcomes in hospitalized patients." (PMID 38732604, 2024). "The administration of intravenous albumin in pressure ulcers was used to address severe hypoalbuminemia, which can occur due to malnutrition or chronic illness, and a high-protein diet was used when possible." (PMID 39766011, 2024). "Albumin, a major component of plasma proteins produced by the liver, is considered a biomarker of malnutrition and inflammation." (PMID 38806039, 2024). "Advanced age, prolonged hospitalization, lower albumin, higher urea, malnutrition, and comorbidities like heart failure, stroke, pneumonia, sepsis, and hypothyroidism were associated with increased mortality." (PMID 38910242, 2024). "Hypoproteinemia and malnutrition result from the body's inflammatory response to malignancy; thus, serum albumin levels can reflect the severity of inflammation in tumor patients." (PMID 38200585, 2024). "Underweight and malnutrition were more common in the control group, while the malnutrition rate among patients in the HP group was lower, and the albumin level was significantly higher than that of patients in other groups." (PMID 39545045, 2024). "Protein-rich supplementation in cases of malnutrition, low total protein, and low serum albumin benefited drugs with high protein binding." (PMID 39770429, 2024). "Albumin, a biological indicator of malnutrition, has been found to decrease with age in the elderly population, which directly links aging with malnutrition." (PMID 39351234, 2024). "Greater arm muscle circumference (AMC) and higher serum albumin were factors for reducing malnutrition by 4.6% and 34.7%, respectively." (PMID 39284026, 2024). "This study aims to investigate the prevalence of malnutrition in different groups of older adults using the F-MNA, anthropometry, and s-albumin and the association between nutritional status and fall risk." (PMID 39519527, 2024). "Albumin, hemoglobin, and potassium are indicators for assessing nutritional status, and low levels of these indicators indicate malnutrition." (PMID 39398953, 2024). "Diabetics with malnutrition had significantly lower levels of BMI, ALB, hemoglobin (Hb), TG, and high‐density lipoprotein cholesterol (HDL‐C), while showing an increase in glycosylated Hb (HbA1c)." (PMID 39364802, 2024). "Risk factors for death included advanced age, prolonged hospital stays, lower albumin, higher urea, malnutrition, and comorbidities like heart failure, stroke, pneumonia, sepsis, and hypothyroidism." (PMID 38910242, 2024). "Our study assessed only the risk of malnutrition using the PNI score, which incorporates serum albumin and lymphocyte count." (PMID 39125277, 2024). "Accordingly, lower levels of serum albumin, an indicator of malnutrition, were significantly more frequently noted in patients presenting decreased MD compliance (p = 0.0008)." (PMID 38492093, 2024). "While it is understood that nutritional status should be evaluated preoperatively, the role of typically used serum albumin and body mass index (BMI) as measures of malnutrition has been equivocal." (PMID 38983939, 2024).
malnutrition (continued). "In late-stage cancer patients, serum albumin synthesis is suppressed by malnutrition and inflammation." (PMID 37836576, 2023). "Compared with albumin, the advantage of prealbumin is that it has a short half-life of 2–3 days; thus, it can be a better indicator of rapid changes in malnutrition status." (PMID 36771359, 2023). "Weight loss alone or in combination with laboratory parameters such as albumin and prealbumin is a major indicator of malnutrition." (PMID 37901305, 2023). "Serum albumin, an indicator of the severity of malnutrition and chronic inflammation, is often used as a part of the frailty criteria." (PMID 37276211, 2023). "Third as albumin is one of the active phase reactants, there is limitation explaining hypoalbuminemia as the sole indicator of malnutrition." (PMID 38036713, 2023). "Traditionally, serum albumin levels have been seen as an indicator of malnutrition and a biomarker of protein stores." (PMID 37380982, 2023). "While not tested on GIST patients, research has shown that low pre-treatment serum albumin, a marker of malnutrition, is an independent adverse predictor of the prognosis of renal cancer patients receiving TKI therapy." (PMID 37627109, 2023). "Based on the factors of the GNRI formula, the BMI and serum albumin levels were significantly lower in the malnutrition group (each p < 0.01)." (PMID 36638132, 2023). "Some studies have pointed out that the albumin level at admission can predict the risk of respiratory failure, which may be related to the fact that low albumin indicates malnutrition, which leads to the atrophy of the diaphragm and respiratory muscles and affects the respiratory function." (PMID 38028763, 2023). "Of all the indicators, the level of serum albumin and hemoglobin in malnutrition group patients diagnosed by all the four tools were significantly lower than well-nourished group patients." (PMID 36761215, 2023). "In patients with ESKD, highly-sensitive CRP and interleukin-6 (IL-6) levels best predict malnutrition, while serum albumin, IL-6, and fetuin A levels best predict mortality." (PMID 37784041, 2023). "Several indices, such as significant weight loss (>10% of basal body weight), low body mass index (BMI) (<18 kg/m2), and reduced levels of albumin (<30 g/L) and pre-albumin (<0.20 mg/dL), can help the diagnosis of malnutrition." (PMID 37509216, 2023). "Undernutrition captured by albumin is another determinant of poor prognosis in cancer patients, and malnutrition can reduce tolerance to adverse events following ICIs." (PMID 35702873, 2023). "Identified low values of anthropometric and biochemical parameters, such as BMI, TS, MAMC, total protein, albumin, urea, creatinine, transferrin, and overall lymphocyte count, indicate the presence of first-degree malnutrition in ALS patients." (PMID 38313408, 2023). "Therefore, although several different diseases cause hypoalbuminemia, such as cirrhosis, malnutrition, nephrotic syndrome, and sepsis, these conditions may not have been the main explanation for the association between serum albumin and height loss observed in this study." (PMID 37700384, 2023). "Serum albumin levels decrease by 15–20% with ageing, further descents seen in cancer patients with malnutrition and inflammation." (PMID 37760638, 2023). "The albumin levels reflect both nutritional status and disease activity and therefore cannot be considered a prognostic marker of malnutrition in IBD." (PMID 37571416, 2023). "Serum albumin is widely recognized as a crucial indicator for evaluating the nutritional status of patients, as its decreased levels often signify malnutrition." (PMID 37838687, 2023). "Decreased albumin levels as a result of malnutrition are the strongest predictor of morbidity and mortality." (PMID 36983369, 2023). "For UC patients with mild, moderate, or severe disease activity, HGB, ALB, and PA were significantly lower in patients with malnutrition." (PMID 37630762, 2023).
malnutrition (continued). "In this study, patients with ALS had lower albumin in their blood compared with control participants, which is typical for first-degree malnutrition." (PMID 38313408, 2023). "Analysis of serum albumin as a continuous variable revealed that patients with HF who had higher serum albumin levels were at a lower odds of malnutrition." (PMID 37034317, 2023). "Our results show that the group of patients with phosphorus <3.6 mg/dL had significant proportions of low income and education, factors that imply higher consumption of unprocessed foods, malnutrition, inflammation and low albumin levels." (PMID 37497059, 2023). "Low albumin is a common malnutrition expression in patients with malignant tumors, which is a typical manifestation of cachexia and is related to the prognosis of patients with various malignant tumors, including esophageal cancer." (PMID 36959779, 2023). "The albumin levels reflect both the nutritional status and disease activity and therefore cannot be considered a prognostic marker of malnutrition in IBD." (PMID 37571416, 2023). "Malnutrition and inflammation suppress albumin synthesis, and a low serum albumin level can reflect disease severity, shown to be a strong predictor of prognosis." (PMID 37685702, 2023). "We would like to highlight the importance of diagnosing malnutrition (low albumin and total proteins in blood), in overweight or obese, sarcopenic patients." (PMID 37686742, 2023). "Because its biological half-life is significantly shorter than that of albumin, it is more sensitive than albumin in evaluating the magnitude of inflammatory reactions, degree of liver function damage, and malnutrition." (PMID 37089882, 2023). "The content of serum albumin and cholesterol is the main index to measure patients' malnutrition, and the lymphocyte level reflects the body's immune function to a certain extent." (PMID 37005959, 2023). "This study found that albumin was used in more than half of studies as a primary or secondary marker of malnutrition." (PMID 37749757, 2023). "For decades, albumin has been determined as an indicator of malnutrition in patients in clinically stable conditions." (PMID 37111024, 2023). "Similar to lactate, serum albumin levels are affected by multiple conditions, including inflammation, malnutrition, and liver cirrhosis." (PMID 37373829, 2023). "Meanwhile, with the decrease in serum albumin, tumor patients will suffer from decreased immunity and malnutrition." (PMID 37836573, 2023). "Malnutrition was found in 68.9% of patients, as assessed based on albumin levels below 3.5 g/dL, and 66.7% met the criteria for malnutrition when total protein levels below 6 g/dL were considered." (PMID 37686742, 2023). "Of note, the majority of issues observed in HPN patients post-bariatric surgery were due to late complications or malnutrition in an ESPEN survey, including low albumin and micronutrient deficiencies." (PMID 36678209, 2023). "When interpreting albumin levels with respect to the nutritional status, it is assumed that a serum level below 3.5 g/dL is indicative of malnutrition, and a serum albumin level <2.1 marks a severe case of malnutrition." (PMID 37111024, 2023). "In particular, studies evaluating the role of serum albumin as a biomarker reflecting the severity of malnutrition have identified lower serum albumin concentrations in patient groups at high risk of malnutrition." (PMID 38249615, 2023). "The finding is in harmony with the studies conducted at Nigeria and Santamaria, Brazil and Greek reported a significantly low level of serum albumin in patients with cancer with malnutrition." (PMID 36869395, 2023). "Studies have shown that malnutrition and inflammation can inhibit the synthesis of ALB and the ALB-related combinations are closely related to the prognosis of malignant tumors." (PMID 36936656, 2023).
malnutrition (continued). "Albumin assays in serum are important for the prognostic assessment of many life-threatening diseases, such as heart failure, liver disease, malnutrition, inflammatory bowel disease, infections, and kidney disease." (PMID 37447868, 2023). "Biochemical markers, such as total protein, albumin, urea, creatinine, transferrin, and total lymphocyte count, offer insights into the intricate metabolic and immunological aspects of malnutrition." (PMID 38313408, 2023). "In other studies, it was reported that diabetic CKD stage 5 (DMCKD5) subjects with PhA values less than 4.17° were reported to show GNRI-assessed malnutrition and low albumin levels (3.13 ± 0.52 g/dL) compared with those with PhA ≥ 4.17°." (PMID 36674360, 2023). "In the 265 patients with moderate disease activity, HGB, ALB, and PA were significantly lower (all p < 0.001), while hsCRP was significantly higher (p < 0.001) in patients with malnutrition." (PMID 37630762, 2023). "The prevalence of low BMI, low serum albumin and malnutrition based on SGA were 42.4%, 62.0% and 74.8%, respectively." (PMID 37220148, 2023). "Based on Albumin levels, 50% of patients were malnourished, with rates of mild, moderate, and severe malnutrition at 28.9%, 17.9%, and 3.2%, respectively." (PMID 37304581, 2023). "Serum albumin level has been identified as an indicator of malnutrition, and hypoalbuminemia is usually defined as an albumin concentration of < 35 mg/dL." (PMID 37081252, 2023). "According to the COUNT score, the normal-nutrition group had higher levels of BMI (23.79 ± 3.25), albumin (42.96 ± 3.13 g/L), total cholesterol (4.80 ± 0.72 mmol/L) and lymphocytes (1.93 ± 0.42 109/L) compared to the malnutrition group (all p < 0.05)." (PMID 38075229, 2023). "First, the GNRI includes albumin, which has been shown to be a valuable biomarker for malnutrition, general health, and chronic inflammation." (PMID 36839241, 2023). "Transferrin has a half-life of approximately 10 days, shorter than albumin and longer than prealbumin, and has been used as a biomarker to evaluate malnutrition status." (PMID 36771359, 2023). "This statement is generally supported since serum markers of malnutrition such as creatinine, prealbumin, or albumin remained unchanged." (PMID 37111217, 2023). "On admission, ESR and CRP were elevated in all patients and malnutrition (serum albumin <3.2g/dl) was observed in five (33.3%) individuals preoperatively." (PMID 36629717, 2023). "We have however, included the presence of dysphagia, as well as albumin and urea levels as proxy indicators for eating problems and malnutrition." (PMID 37118683, 2023). "In a study evaluating TLC and albumin in surgical patients, malnutrition was higher than in our study (73.9% by TLC)." (PMID 38002791, 2023). "Several blood biomarkers, including albumin, prealbumin, hemoglobin, total cholesterol and total protein, are indicators of malnutrition, even in the presence of chronic inflammation." (PMID 37239661, 2023). "Albumin is a well-known indicator of the nutritional status of the body, and many studies have concluded that low albumin is a sign of malnutrition in the body." (PMID 37361569, 2023). "Serum albumin levels are affected by diverse conditions such as substantial chronic liver diseases, serious malnutrition, and protein-losing enteropathy or nephropathies, in addition to the degree of inflammatory burden." (PMID 37373863, 2023). "Prior studies have shown that serum concentration of albumin is strongly correlated to the Mini Nutritional Assessment in older adults, and low albumin usually indicates the body’s malnutrition." (PMID 37957767, 2023). "As expected, HGB, ALB, and PA were significantly lower in the malnutrition group, and hsCRP was significantly higher in the malnutrition group (all p < 0.001)." (PMID 37630762, 2023).